CCDC102A (coiled-coil domain containing 102A)
Synonyms: MGC10992
Tractability: PROTAC: its protein half-life has been measured.
Gene: Protein-coding gene on chromosome 16 (57,511,999 to 57,537,163, reverse strand). Ensembl gene ENSG00000135736.
Subcellular location (Human Protein Atlas): Nucleoplasm; Nuclear bodies
Gene Ontology:
Molecular function: protein binding
Cellular component: myosin complex
Genetic constraint (gnomAD): Loss-of-function variants: 28 observed, 33.97 expected, observed/expected ratio (o/e) 0.82, 90% interval 0.61 to 1.13. The upper end of that interval is the gene's LOEUF score, 1.13, which puts it in group 4 of 6, group 1 being the genes least tolerant of losing a copy. Missense variants: 584 observed, 533.21 expected, observed/expected ratio (o/e) 1.1, 90% interval 1.02 to 1.17. Synonymous variants: 244 observed, 217.65 expected, observed/expected ratio (o/e) 1.12, 90% interval 1.01 to 1.25.
Homologues: Orthologues: chimpanzee CCDC102A (99% identical), macaque CCDC102A (99% identical), guinea pig CCDC102A (94% identical), dog CCDC102A (93% identical), pig CCDC102A (93% identical), mouse Ccdc102a (92% identical), rat Ccdc102a (92% identical), zebrafish ccdc102a (67% identical), tropical clawed frog ccdc102a (63% identical). Paralogues in human: CCDC102B (40% identical), MYH1 (29% identical), MYH2 (29% identical), MYH6 (29% identical), MYH7 (29% identical), MYH7B (29% identical), MYH3 (29% identical), MYH4 (29% identical), MYH8 (29% identical), MYH13 (28% identical), MYH15 (28% identical), MYH14 (27% identical), and 32 more.
Diseases named in the same sentence as CCDC102A in open-access papers:
CCDC102A is named in the same sentence as 1 disease in open-access papers, as found by Europe PMC text mining. Sharing a sentence is not in itself a finding about the gene and the disease.
CCDC102A shares sentences with these, for which no sentence is quoted: cancer (1 paper).